CHDH (choline dehydrogenase)
Description:
Catalyzes the dehydrogenation of choline to betaine aldehyde in the mitochondria (By similarity). Involved in mitochondrial autophagy after mitochondrial damage.
Tractability: PROTAC: ubiquitination databases record sites on it; its protein half-life has been measured.
Gene: Protein-coding gene on chromosome 3 (53,812,335 to 53,846,466, reverse strand). Ensembl gene ENSG00000016391.
Subcellular location: Mitochondrion inner membrane; Mitochondrion outer membrane
Subcellular location (Human Protein Atlas): Mitochondria; Nucleoli
Pathways (Reactome):
Metabolism: Choline catabolism
Gene Ontology:
Molecular function: protein binding; choline dehydrogenase activity; flavin adenine dinucleotide binding; oxidoreductase activity, acting on CH-OH group of donors
Biological process: choline catabolic process
Cellular component: mitochondrial inner membrane; mitochondrial outer membrane; mitochondrion
Genetic constraint (gnomAD): Loss-of-function variants: 40 observed, 47.7 expected, observed/expected ratio (o/e) 0.84, 90% interval 0.65 to 1.09. The upper end of that interval is the gene's LOEUF score, 1.09, which puts it in group 4 of 6, group 1 being the genes least tolerant of losing a copy. Missense variants: 813 observed, 777.95 expected, observed/expected ratio (o/e) 1.05, 90% interval 0.99 to 1.11. Synonymous variants: 364 observed, 326.46 expected, observed/expected ratio (o/e) 1.12, 90% interval 1.02 to 1.22.
Homologues: Orthologues: chimpanzee CHDH (99% identical), macaque CHDH (97% identical), pig CHDH (89% identical), guinea pig CHDH (88% identical), rabbit CHDH (88% identical), dog CHDH (86% identical), mouse Chdh (83% identical), rat Chdh (82% identical), zebrafish chdh (71% identical), Caenorhabditis elegans chdh-1 (52% identical), tropical clawed frog CHDH (34% identical), Drosophila melanogaster ninaG (27% identical).
Diseases named in the same sentence as CHDH in open-access papers:
CHDH is named in the same sentence as 42 diseases in open-access papers, as found by Europe PMC text mining. Sharing a sentence is not in itself a finding about the gene and the disease. The quoted sentences say what the papers report.
breast carcinoma (9 papers, 2012 to 2025). "Recent studies have revealed that CHDH is associated with the development of various human pathologies, including male infertility, homocystinuria, breast cancer, and metabolic syndrome, and that CHDH plays a crucial role in mitochondrial autophagy." (PMID 39764560, 2025). "Higher dietary intake of choline reduced the risk of breast cancer and the carrier minor T allele of the CHDH rs12676 (+432G>T) SNP was correlated to an increased risk of breast cancer." (PMID 37600654, 2023). "In the expanded cohort study, low expression of CHDH was associated with a higher risk of recurrence after tamoxifen monotherapy in the breast cancer patient cohort." (PMID 37600654, 2023). "Choline is an essential nutrient required for methyl group metabolism, and CHDH is associated with an increased risk of breast cancer." (PMID 33456371, 2020). "rs12676 (G233T), a non-synonymous SNP located in the CHDH coding region, is associated with increased susceptibility to dietary choline deficiency and risk of breast cancer." (PMID 22558321, 2012). "Moreover, we analysed the association between TNM staging and CHDH protein expression in breast cancer." (PMID 40928004, 2025). "CHDH as a prognostic biomarker for evaluating breast cancer may be associated with ER+ breast cancer." (PMID 40928004, 2025). "On the other hand, glycine betaine plays important roles as a primary intracellular osmoprotectant, and impairments in human CHDH activity have been associated with various pathologies, including male infertility, homocystinuria, metabolic syndrome, cardiovascular diseases, and breast cancer." (PMID 36980356, 2023). "Aberrant expression of CHDH and IL17βR has been associated with breast cancer survival prognosis." (PMID 22558321, 2012). "The CHDH minor T allele is associated with increased susceptibility to developing clinical symptoms of dietary choline deficiency (steatosis and muscle cell damage) as well as increased risk of breast cancer." (PMID 22558321, 2012). "Besides, CHDH was associated with an increased risk of breast cancer and esophageal cancer." (PMID 38376420, 2024). "The experimental results showed that CHDH protein was highly expressed in a variety of breast cancer cell lines compared to normal breast cells MCF‐10A, especially in MDA‐MB‐453 cells." (PMID 40928004, 2025). "The findings indicated that the expression level of the CHDH protein was significantly increased in breast cancer tissues in comparison to normal tissues." (PMID 40928004, 2025). "The application of an IL17RB antibody and the CREB inhibitor 666‐15 effectively abolished CHDH‐mediated migration of breast cancer cells in vitro." (PMID 40928004, 2025). "The results showed that CHDH expression in breast cancer tissues was significantly higher than in comparable normal tissues in the online database." (PMID 40928004, 2025). "The silencing of CHDH expression resulted in a reduction of breast cancer cell migration, while the overexpression of CHDH facilitated increased migration and tumour metastasis in vivo." (PMID 40928004, 2025). "Our research indicates that CHDH protein expression is markedly elevated in breast cancer tissues compared to normal tissues, and this expression is positively correlated with the tumour node metastasis (TNM) stage of breast cancer." (PMID 40928004, 2025). "In a study of novel prognostic biomarkers for breast cancer, CHDH expression was found to be regulated by oestrogen." (PMID 40928004, 2025). "Investigations into the underlying mechanisms revealed that CHDH influences the expression of IL17RB and activates Cyclic‐AMP Response Element‐Binding Protein (CREB), thereby mediating breast cancer metastasis." (PMID 40928004, 2025). "The expression of CHDH in normal mammary cells and breast cancer cell lines was detected by Western blot." (PMID 40928004, 2025). "The results showed that IL17RB expression was increased in breast cancer cell lines overexpressing CHDH." (PMID 40928004, 2025).
breast carcinoma (continued). "Furthermore, CHDH levels were found to be significantly higher in breast cancer cell lines relative to normal breast cells." (PMID 40928004, 2025). "Consequently, this study seeks to investigate the potential of the CHDH molecule as a novel biomarker for breast cancer metastasis." (PMID 40928004, 2025). "However, the specific role of CHDH in the metastasis and progression of breast cancer (BC) has been less thoroughly investigated." (PMID 40928004, 2025). "Collectively, we conclude that overexpression of CHDH facilitated breast cancer metastasis in vivo." (PMID 40928004, 2025). "As CHDH has been shown to promote BC cell migration in vitro, we investigated the effect of overexpression of CHDH on tumour growth and metastasis in vivo by using a nude mice breast cancer transplantation model." (PMID 40928004, 2025). "A study on CHDH as a prognostic biomarker for breast cancer found that its expression is regulated by estrogen and its prognostic function may be mediated by estrogen-dependent pathways." (PMID 37600654, 2023). "CHDH strongly predicted clinical outcome in breast cancer patients receiving tamoxifen monotherapy." (PMID 33456371, 2020). "In addition, we validated that Choline dehydrogenase (CHDH) has significant lower expression in HER2 positive breast cancers in TCGA patient samples." (PMID 29458327, 2018). "Importantly, CHDH expression in breast cancer is also regulated by oestrogen; both CHDH and acetylcholine are involved in choline metabolism, suggesting a potential association between CREB1 and CHDH." (PMID 40928004, 2025). "A 5-gene assay was also developed quantifying the expression of CHDH, HOXB13, IL17BR, MIB1 and MKI67 to identify a subgroup of early stage estrogen receptor–positive breast cancer patients with very poor outcome despite endocrine therapy." (PMID 23468873, 2013).
fatty liver (3 papers, 2014 to 2025). "Additionally, it has been established that betaine-elicited inhibition of CHDH and activation of BHMT can collectively enhance catabolism, but decrease the synthesis of betaine in the liver in ApoE−/− mice with hepatic steatosis." (PMID 25010553, 2014). "Low choline diet led to transcriptional changes in peripheral lymphocytes.Gene signature associated with the presence or absence of organ dysfunction (fatty liver and elevated plasma CRP).SNPs in MTHFD1, CHDH and PEMT influence the diet-induced changes in gene expression profile." (PMID 40821837, 2025).
male infertility (3 papers, 2023 to 2025). The inability of the male to effect fertilization of an ovum after a specified period of unprotected intercourse. "Different studies have found that CHDH is closely associated with the development of several diseases, including malignancies, psychiatric disorders, male infertility, tooth agenesis and hyperhomocysteinemia." (PMID 37600654, 2023). "SNP-induced changes in CHDH activity may lead to male infertility." (PMID 37600654, 2023).
pancreatic cancer (3 papers, 2018 to 2023). "LL genotypes with the CHDH L78R SNP showed significant protection against pancreatic cancer compared to the reference RR allele." (PMID 37600654, 2023). "Subjects that carried the LL genotype (nucleotide TT) of the CHDH L78R SNP were found to be at decreased risk for pancreatic cancer both prior to (OR = 0.29; 95% CI 0.12–0.76) and after adjusting for age and sex (OR = 0.29; 95% CI 0.10–0.84)." (PMID 29474406, 2018). "In conclusion, in this study, we have explored several SNPs in genes in the folate pathway for their association with both folate status and pancreatic cancer, and have identified that the LL variant of the L78R SNP in CHDH is associated with a decreased risk for pancreatic cancer." (PMID 29474406, 2018). "A recent study showed a significant difference in the distribution of CHDH rs12676 (+432G>T) SNP genotypes in pancreatic cancer patients compared to healthy individuals." (PMID 37600654, 2023). "As autophagy has been shown to promote pancreatic cancer, we postulate that the inability of the L78 form of CHDH to stimulate autophagy may lead to protection against pancreatic cancer development." (PMID 29474406, 2018). "Since autophagy has been shown to promote pancreatic cancer, it is speculated that the L78 form of CHDH may not stimulate autophagy to inhibit pancreatic cancer." (PMID 37600654, 2023).
hepatocellular carcinoma (2 papers, 2023 to 2025). A malignant tumor that arises from hepatocytes. "This suggests that CHDH may be a promising biomarker and a potential therapeutic target for hepatocellular carcinoma." (PMID 37600654, 2023).
type 2 diabetes (2 papers, 2012 to 2022). "Among NW subjects, we observed nominal association of MTHFR-rs1801133, MTHFR-rs9651118, CHDH-rs4563403, CBS-rs706208, and MTHFD1L-rs1555179 with type 2 diabetes (P value range= 0.002–0.04)." (PMID 21960995, 2012).
atherosclerosis (1 paper, 2022). A disease characterized by the build-up of fatty material and calcium deposition in the arterial wall resulting in partial or complete occlusion of the arterial lumen. "CHDH modification of aspartic acid and NO_SMX_SIMD modification of cysteine have not been reported to be related to atherosclerosis and may act as potential modification sites." (PMID 36358920, 2022).
colitis (1 paper, 2024). Inflammation of the colon. "Western blotting analysis demonstrated a reduction in the protein expression levels of ALDH5A1, PDK2, and CHDH in the colitis lesions of mice administered with DSS." (PMID 38376420, 2024). "Collectively, our findings indicate that the influence of PDK2, CHDH, and ALDH5A1 on the advancement of DSS-induced colitis in mice is potentially mediated through the regulation of macrophage infiltration." (PMID 38376420, 2024). "The results demonstrated a downregulation of mRNA and protein expression levels of PDK2, CHDH, and ALDH5A1 in colitis cells and tissues, which aligns with our previous bioinformatic analysis." (PMID 38376420, 2024). "And the results also demonstrated that CD86 exhibited higher expression in mouse colitis lesions, whereas PDK2, CHDH, and ALDH5A1 displayed lower expression in these lesions." (PMID 38376420, 2024). "Ultimately, the verification of the expression of signature genes (ALDH5A1, CHDH, and PDK2) and their co-expression with M1 macrophages (CD86) was accomplished through the construction of inflammatory cell and colitis models." (PMID 38376420, 2024). "Additionally, the expression levels of PDK2, CHDH, and ALDH5A1 were lower in colitis tissues, which aligns with the results obtained from the bioinformatic analysis." (PMID 38376420, 2024).
colorectal cancer (1 paper, 2025). A primary or metastatic malignant neoplasm that affects the colon or rectum. "We used the P4HA inhibitor 1,4‐DPCA and the C‐JUN inhibitor SP600125 to treat colorectal cancer metastasis, either separately or in combination, and the results showed favorable therapeutic effects on CHDH‐mediated metastasis." (PMID 39764560, 2025). "However, the functional role of CHDH in colorectal cancer (CRC) metastasis remains unreported." (PMID 39764560, 2025). "According to our results, CHDH was upregulated in colorectal cancer tissues compared to normal tissues and positively correlated with TNM stage." (PMID 39764560, 2025).
diabetic neuropathy (1 paper, 2023). A chronic, pathological complication associated with diabetes mellitus, where nerve damages are incurred due to diabetic microvascular injury involving small blood vessels that supply these nerves, resulting in peripheral and/or autonomic nerve dysfunction. "Similarly, GeneCards also reports an association of kidney function with other top predicted Diabetic Neuropathy genes having no PubMed support, including HAMP (predicted gene #2) and CHDH (predicted gene #8)." (PMID 36791052, 2023).
Down syndrome (1 paper, 2023). "However, the cholinesterase genotype combination PEMT - 744GC/CHDH +432GG/BHMT +742GG was significantly higher in mothers of children with Down syndrome." (PMID 37600654, 2023).
Infertility (1 paper, 2012). "Together, this evidence indicates that altered CHDH activity due to rs12676 genotype may be an underlying cause of iodiopathic male factor infertility in men." (PMID 22558321, 2012).
schizophrenia (1 paper, 2023). A major psychotic disorder characterized by abnormalities in the perception or expression of reality. "The expression levels of CHDH rs35518479 in postmortem brains of schizophrenia patients were found to be significantly different from normal controls by eQTL analysis." (PMID 37600654, 2023).
cancer (11 papers, 2019 to 2025). A tumor composed of atypical neoplastic, often pleomorphic cells that invade other tissues. "Interestingly, CHDH knockdown was previously reported to cause a cell cycle phenotype in siRNA screening, suggesting the possibility that betaine synthesis could be important to cancer cell proliferation." (PMID 33249526, 2020). "Moreover, we described the regulatory role of CHDH on the progression of different types of malignant tumors." (PMID 37600654, 2023). "Therefore, the role of CHDH in producing metabolic pathway products in cancer cells needs to be further investigated." (PMID 37600654, 2023). "Moreover, we will describe the regulatory role of CHDH on the progression of different types of malignant tumors." (PMID 37600654, 2023). "Nevertheless, expression of CHDH coinciding with betaine synthesis in transformed cells may indicate a previously unknown fate of choline in cancer cells." (PMID 33249526, 2020). "In the betaine part, the expression of SLC44A4, CHDH, and BHMT was disordered across cancers and had a general downward trend." (PMID 31828117, 2019).
tumor (11 papers, 2017 to 2026). "In recent years, an increasing number of studies have focused on CHDH and found a close association with the pathogenesis of various diseases, including tumor prognosis." (PMID 37600654, 2023). "The involvement of Choline Dehydrogenase (CHDH) in metabolic disorders and tumour progression has garnered significant scholarly interest." (PMID 40928004, 2025). "We noticed that elevated CHDH expression levels positively correlated with tumor biopsies with a high TNM stage." (PMID 39764560, 2025). "Altogether, these findings suggest that CHDH acts a crucial role in regulating tumor migration in vitro." (PMID 39764560, 2025). "To further evaluate the effect of CHDH on tumor migration, we ectopically expressed CHDH in RKO and LOVO cells with low CHDH expression and found that the efficiency of CHDH overexpression was high, as detected using immunoblotting." (PMID 39764560, 2025). "Given that CHDH has the property of promoting tumor cell metastasis in vitro, we investigated the corresponding in vivo effects in a xenograft mouse model." (PMID 39764560, 2025). "To investigate the functional role of CHDH in BC tumour migration in vitro, we designed and constructed a CHDH‐specific shRNA and constructed a cell line with stable knockdown of CHDH in MDA‐MB‐453 by lentiviral system." (PMID 40928004, 2025). "Taken together, our results suggest that CHDH plays an important role in regulating tumour migration in vitro." (PMID 40928004, 2025). "The results showed that CHDH expression was elevated in tumor biopsy tissues compared to that in normal tissues." (PMID 39764560, 2025). "The observation that betaine is formed in tumor-derived cells, likely via the CHDH enzyme, raises questions about the function of betaine in these cells." (PMID 33249526, 2020). "Thus, these cell lines appear to be suitable models to determine the effect of CHDH on tumor migration in vitro." (PMID 39764560, 2025). "CHDH exerts a vital role in the pathogenesis and progression of several tumor types." (PMID 39764560, 2025). "Moreover, the IHC results showed higher levels of IL17RB and CREB1 expression in tumours of mice overexpressing CHDH." (PMID 40928004, 2025). "CHDH knockdown suppressed cell migration in vitro and tumor metastasis in vivo." (PMID 39764560, 2025). "Collectively, our results suggest that CHDH promotes tumor metastasis in vivo." (PMID 39764560, 2025). "We hypothesised that CHDH activates CREB1 by promoting the expression of IL17RB, which may reveal a novel mechanism by which CHDH promotes tumour progression." (PMID 40928004, 2025). "Although the role of JNK/c‐Jun in tumors has been extensively studied, its role in CHDH‐mediated tumor progression remains unclear." (PMID 39764560, 2025). "Together, these findings demonstrate that CHDH may be a potential factor promoting tumour function and is highly expressed in human BC tissues." (PMID 40928004, 2025). "Similarly, ectopic CHDH expression enhanced cell migration in vitro and tumor metastasis in vivo." (PMID 39764560, 2025). "Therefore, this cell line could serve as a suitable model to determine the effect of CHDH on tumour migration in vitro." (PMID 40928004, 2025). "This could uncover a new mechanism through which CHDH facilitates tumor progression." (PMID 39764560, 2025). "To explore the functional role of CHDH in tumor migration in vitro, we knocked down CHDH expression in HCT116 and SW620 cells using CHDH‐specific short hairpin RNAs (shRNAs)." (PMID 39764560, 2025). "CHDH expression was significantly higher in CRC compared to normal tissues and showed a positively correlation with CRC tumor‐nodes‐metastasis stage." (PMID 39764560, 2025). "We found that CHDH is highly expressed in CRC and promotes cell migration in vitro and tumor metastasis in vivo." (PMID 39764560, 2025). "We also investigated the correlation between CHDH expression and tumor‐nodes‐metastasis (TNM) stage of tumor biopsies." (PMID 39764560, 2025).
tumor (continued). "However, the function of CHDH in CRC has not been reported, and its relationship with tumor metastasis is unclear." (PMID 39764560, 2025).